SOX2 (SRY-box transcription factor 2)
Diseases named in the same sentence as SOX2 in open-access papers (continued):
Sharing a sentence is not in itself a finding about the gene and the disease.
cervical cancer (continued). "SOX2 is acknowledged as a tumor promoter across various cancer types, including prostate and cervical cancers, primarily by maintaining the stem-like properties of cancer cells that drive tumor progression and dissemination." (PMID 39976818, 2025). "In cervical carcinogenesis, CD49f is assumed as a marker of cervical cancer stem cells potentially linked with CD133 and SOX2 expression and preferentially targeted by high-risk HPVs." (PMID 40083005, 2025). "This study elucidates the regulatory mechanism of the miR-122-5p/UCA1/SOX2 axis in the self-renewal of cervical cancer stem cells, offering a significant theoretical foundation for the advancement of novel therapeutic targets." (PMID 40710326, 2025). "SRY-Box transcription factor 2 (SOX2), a known oncogene in cervical cancer, showed a positive correlation with DDR1 and regulated DDR1 transcription, contributing to the elevated expression of DDR1 in cervical cancer." (PMID 39567474, 2024). "It seemed to suggest that DDR1 was the downstream of SOX2, when SOX2 acted as an oncogene in cervical cancer." (PMID 39567474, 2024). "With the current results, we demonstrated that DDR1 was transcriptionally regulated by SOX2 and facilitated the transfer of cervical cancer cell." (PMID 39567474, 2024). "As a marker of cancer stem cells, SOX2 is related to a worse prognosis in advanced cancer, and is considered as a potential oncogenic factor in cervical cancer." (PMID 39567474, 2024). "Venn diagram displayed the genes that were modulated by SOX2 and differently expressed in cervical cancer." (PMID 39567474, 2024). "In consideration of the regulating transcription function of SOX2, it was worth investigating what was regulated by it to promote cervical cancer development." (PMID 39567474, 2024). "In cervical cancer, SOX2 expression was significantly increased in radiation-resistant cells screened by multiple radiotherapy treatments." (PMID 37213675, 2023). "All of these results suggested that SNAI2 blocked the nuclear translocation of β-catenin by inhibiting EPCAM expression, further suppressing the expression of c-Myc and SOX2, and ultimately attenuating the stem-like phenotype in cervical cancer cells." (PMID 36674577, 2023). "First, the protein levels of β-catenin and the Wnt/β-catenin signaling pathway target genes c-Myc and SOX2 were detected in SNAI2-modified cervical cancer cells." (PMID 36674577, 2023). "NFYA promoted cell proliferation and tumorigenic properties by transcriptional activation of SOX2 in cervical cancer." (PMID 35409328, 2022). "Silencing of UBE2T downregulated protein expression of SOX2, Oct-4, and Nanog in cervical cancer cells reduced self-renewal capacity." (PMID 34703898, 2021). "Previous reports demonstrated that SOX2-positive cervical cancer cells shared all the characteristics with cancer stem cells including self-renewal, differentiation, and tumor-initiating properties." (PMID 34539782, 2021). "Then, we tested LGR6, β-catenin, TCF7L2, c-Myc, OCT4, and SOX2 in 15 cervical cancer tissues by IHC." (PMID 34489551, 2021). "For instance, hypomethylation of the promoter region of lncRNA SOX21-AS1 can make it overexpress, thereby enhancing the inhibitory effect of lncRNA SOX21 on lncRNA SOX2 and inhibit the progression of cervical cancer." (PMID 34583640, 2021). "The expression of SOX2 is correlated with the degree of differentiation of SCC, and up-regulation of SOX2 has been shown to enhance cervical cancer cell invasion and migration in vitro." (PMID 33789601, 2021). "Here, we found a new binding site for NF‐YA in the SOX2 promoter, resulting to the transcription in cervical cancer cells." (PMID 32954681, 2020). "High risk human papillomavirus (HR-HPV) promotes self-renewal by upregulating OCT-3/4, NANOG, and SOX2 expression to maintain the cervical cancer stem cell (CCSC) in the cervical cancer." (PMID 32178477, 2020).
cervical cancer (continued). "The luciferase reporter assay combined with mutagenesis analyses and Western blotting showed that NF‐YA trans‐activated the expression of SOX2 in cervical cancer." (PMID 32954681, 2020). "While SOX2 expression shows a favorable prognosis in non-small cell lung cancer and cervical cancer." (PMID 32104175, 2020). "At last, the IHC assay of cervical cancer tissues from patients (N = 10) determined the positive correlation between NF‐YA and Ki‐67/SOX2 (P < 0.05)." (PMID 32954681, 2020). "In cervical carcinoma, STAT3 upregulates the stem-like characteristics of cervical cancer cells by increasing the expression of the stemness supporting markers such as Sox2, Oct4, and Nanog." (PMID 31935877, 2020). "We showed that the strong ratio of SOX2 expression in cervical cancer cells was 80%, but the ratio of c-MYC was 35%." (PMID 33089188, 2020). "It was reported that Hedgehog signaling acts upstream of Sox2 in cancer stem cells, and Sox18 is a target gene of hedgehog signaling in cervical carcinoma." (PMID 32674056, 2020). "Specifically, the expression of ALDH1, Sox2, CD49f, Nanog, and Oct4 was significantly up-regulated in cervical cancer cells derived CSCs." (PMID 30791957, 2019). "Collectively, our data identified NF-YA box CCAAT as a key cis-element in the SOX2 promoter, suggesting that NF-YA is a potent cellular regulator in the maintenance of SOX2-positive cervical cancer stem cell by specific transcriptional activation of SOX2." (PMID 31365524, 2019). "In our previous study, SOX2-positive cells isolated from the cervical cancer cell lines SiHa and C33A were found to exhibit self-renewal, differentiation, and tumor initiating properties, which are major characteristics of CSCs." (PMID 31365524, 2019). "Our previous study identified SOX2 as a marker in cervical cancer stem cells driven by a full promoter element of SOX2 EGFP reporter." (PMID 31365524, 2019). "Researches have strongly correlated SOX2 to cancer hallmarks, and SOX2 has been regarded to induce cellular proliferation (breast and cervical cancers)." (PMID 31516388, 2019). "The transcript analysis of CSCs enriched from cervical cancer cell lines (CaSki and HeLa) revealed a significant upregulation of SOX2." (PMID 29777148, 2018). "In conclusion, we have uncovered an intriguing liaison among let-7i-5p, miR-181a-2-3p and EGF/PI3K/SOX2 axis, which is vital for the maintenance of CSCs in cervical cancer." (PMID 29777148, 2018). "Depletion of P16INK4A promoted chemoresistance and radioresistance of cervical cancer cells increased the expression of SOX2 and ALDH1A1 and exhibited higher self-renewal ability." (PMID 30150594, 2018). "It has been reported that some oncogenes and transcription factors are correlated with cervical cancer and likely involved in the development and progression of cervical cancer, such as SOX2, KLF4, OCT4 and NANOG." (PMID 28514765, 2017). "In fact, high levels of SOX2 have been demonstrated in cervical cancer and particularly, in a subpopulation of tumor initiating cells with stem-like properties." (PMID 28678184, 2017). "The cervical cancer cell lines, SiHa and C33A, were transfected with a plasmid containing the human SOX2 gene, and were sorted using a SOX2 antibody and FACS." (PMID 27343550, 2017). "Both in vitro and in vivo studies have shown that cervical cancer cells with SOX2 over-expression have increased cell proliferation, clonogenicity, and tumourigenicity." (PMID 27343550, 2017). "There is significantly higher nuclear SOX2 expression in cervical carcinoma than in normal cervix tissues." (PMID 27343550, 2017). "Further, another investigation revealed that an enriched cervical cancer cellular pool possesses tumorigenic capacity and expresses stemness-related genes (Oct-3/4 and Sox2)." (PMID 26832364, 2016). "ALDH, CD133, and Sox2 have been identified as the first putative CSC markers in human cervical carcinoma." (PMID 26832364, 2016).
cervical cancer (continued). "OCT4 high expression showed poor disease-free survival and overall survival while SOX2 high expression showed favorable overall survival in patients with cervical cancer." (PMID 26706028, 2015). "In conclusion, this study investigated the immunohistochemical expression of OCT4 and SOX2 in large number of cervical cancer patients by means of image analysis for IHC scoring." (PMID 26706028, 2015). "Among patients with high Sox2 expression, 18 % had recurrent cancer, whereas only 3 % patients with low Sox2 expression did, implicating a correlation of Sox2 expression and cervical cancer progression." (PMID 26499463, 2015). "The aims of this work were therefore to evaluate the expression pattern of Msi1, ALDH1, Sox2, and CD49f in cervical cancer tissues and to determine their significance in predicting the prognosis in cervical cancer patients." (PMID 26499463, 2015). "Cox regression analysis confirmed that OCT4, and SOX2 expression was an important prognostic indicator in cervical cancer." (PMID 26706028, 2015). "Further research is required to clarify the prognostic significance of SOX2 in cervical cancer and variation in prognosis according to cell type." (PMID 26706028, 2015). "High expression of Msi1, ALDH1, and Sox2, and low expression of CD49f predict poor prognosis for cervical cancer patients receiving postoperative chemotherapy." (PMID 26499463, 2015). "The CD49f was expressed at the much higher level in EGFP+ than that in EGFP− SiHa and C33A cells, respectively, suggesting both Sox2 and CD49f are the appropriate marker for cervical cancer stem cells." (PMID 24489842, 2014). "Taken together, all these results indicate that endogenous Sox2-expressing cervical cancer cells have significantly enhanced tumor formation ability because the EGFP+ SiHa and C33A cells contained more CSCs than EGFP- cells." (PMID 24489842, 2014). "In the present study, we stably transfected two cervical cancer cell lines, SiHa and C33A, with a plasmid containing the human Sox2 transcriptional elements driving EGFP expression." (PMID 24489842, 2014). "We chose to stain SOX2 protein in these biopsies as it has been reported to be upregulated in human cervical cancer stem cells and in SCCC." (PMID 25531390, 2014). "In conclusion, we first isolated CSCs from cervical cancer cell lines using a functional nuclear marker, Sox2." (PMID 24489842, 2014). "Sox2-positive cells isolated from the cervical cancer cell lines SiHa and C33A were found to exhibit self-renewal, differentiation, and tumor initiating properties, which are major characteristics of CSCs." (PMID 24489842, 2014). "The differentiation, self-renewal and tumor formation abilities, as well as the expression of the stemness and the EMT related genes of the Sox2-positive and the Sox2-negative cervical cancer cells were characterized in vitro and in vivo." (PMID 24489842, 2014). "Sox2 expression was characterized in four human cervical cancer cell lines (HeLa, SiHa, CaSki, and C33A) using the pSox/EGFP system as well as western blot and immunocytochemical analysis." (PMID 24489842, 2014). "Overall, the results obtained using the pSox2/EGFP system were consistent with the Sox2 expression results from western blot and immunocytochemical analysis in all four cervical cancer cell lines." (PMID 24489842, 2014). "This study is the first to establish a functional link between endogenous Sox2 expression and CSCs in cervical carcinomas." (PMID 24489842, 2014). "Taken together, all these results indicated that cells expressing endogenous Sox2 are CSCs in cervical carcinomas." (PMID 24489842, 2014). "When Sox2 was stably expressed in cervical cancer cells (SiHa and HeLa), overexpressing cells had increased proliferation, clonogenicity, and tumorigenicity in vitro and in vivo." (PMID 22284662, 2012). "A pivotal role for SOX2 in the process of cervical cancer has been found in the literatures." (PMID 39567474, 2024).
cervical cancer (continued). "Our previous study demonstrated that SOX2 promoted the progress of cervical cancer." (PMID 39567474, 2024). "Firstly, increased DDR1 and SOX2 were verified in cervical cancer samples." (PMID 39567474, 2024). "In addition, it was found that in cervical cancer, SOX2 can modulate cellular radioresistance by altering cell proliferation, apoptosis, and cell cycle changes after radiation through the Hedgehog signaling pathway." (PMID 37213675, 2023). "SOX2-positive cells derived from cervical cancers show cancer stem cell characteristics." (PMID 35945296, 2022). "Moreover, UBE2T overexpression cervical cancer cells demonstrated enhanced self-renewal capacity with upregulation of SOX2, Oct-4, and Nanog protein." (PMID 34703898, 2021). "Our previous studies have indicated that ALDH might be a marker of cervical CSCs and some stem cell-associated genes such as SOX2, OCT4, and LGR5 are closely associated with tumorigenesis in cervical cancer." (PMID 34489551, 2021). "Furthermore, we used western blotting to detect LGR6, β-catenin, TCF7L2, c-Myc, and SOX2 in 16 cervical cancer samples." (PMID 34489551, 2021). "Here, our study demonstrated that NF‐YA was up‐regulated during the progression of cervical cancer, which was essential for the promotion of cell proliferation, tumorigenicity and stemness properties by transcriptional activation of SOX2 protein in cervical cancer." (PMID 32954681, 2020). "As the activator of SOX2, high expression of NF‐YA in cervical cancer was positive related to it and promoted the stemness of cervical cancer cells, suggesting that NF‐YA might be another biomarker or regulator of cervical CSC." (PMID 32954681, 2020). "However, This plasmid was so large (approximately 16kb) that the transfection efficiency in cervical cancer cell lines was so low for sorting the endogenous SOX2-positive cells." (PMID 31365524, 2019). "Furthermore, overexpression of NF-YA in primitive cervical cancer cells SiHa and C33A significantly activated the transcription and the protein expression of SOX2." (PMID 31365524, 2019). "Next, we further investigated whether the P16INK4A expression plus stem cell marker (SOX2 or ALDH1A1) was a good predictor of survival outcomes of cervical cancer patients treated with radiotherapy." (PMID 30150594, 2018). "However, in both the cervical cancer cell lines, HeLa and CaSki, the expression of SOX2 was significantly upregulated." (PMID 29777148, 2018). "The further studies on cervical cancer tissue samples and in vivo may help develop let-7i-5p, miR-181a-2-3p or SOX2 as potential targets for therapy against cervical CSCs." (PMID 29777148, 2018). "Furthermore, HOXA11-AS knockdown decreased expression of stemness genes, SOX2, Oct-4, and Nanog in cervical cancer cells." (PMID 27792998, 2016). "In addition, SOX2 was reported to enhance tumor formation ability and to serve as a nuclear marker for cervical cancer stem cells, and ALDH1 was reported to be a cytoplasmic maker for cervical cancer stem cells." (PMID 27036045, 2016). "Here, we investigate the expression and clinical significance of OCT4 and SOX2 in cervical cancer." (PMID 26706028, 2015). "Our findings suggest further investigation into OCT4 and SOX2 as biomarkers in cervical cancer." (PMID 26706028, 2015). "Sox2-positive population of cervical cancer cells show characteristics of tumor-initiating cells." (PMID 26499463, 2015). "High expression of SOX2 was reported to be associated with a lack of cell differentiation and to contribute cell migration and invasion in cervical cancer cell line." (PMID 26706028, 2015). "OCT4 and SOX2 expression was higher in cervical cancer than normal cervix (both p < 0.001)." (PMID 26706028, 2015). "Considering previous results and our contradictory survival data, OCT4 and SOX2 might function independently or inhibit activity during tumor progression, and eventually lose their connection in cervical cancer." (PMID 26706028, 2015).
cervical cancer (continued). "Sox2-expressing cervical cancer cells shared all the properties of CSCs." (PMID 24489842, 2014). "We demonstrated that Sox2-positive cervical cancer cells shared all the characteristics of CSCs." (PMID 24489842, 2014). "Furthermore, further experiments should be designed to figure out which is the best cervical cancer stem cell population isolated by either Sox2 or CD49f or by both." (PMID 24489842, 2014). "Therefore, the cells that endogenously express Sox2 that were isolated from the SiHa and C33A cell lines are CSCs in cervical carcinomas." (PMID 24489842, 2014). "Our previous studies have indicated that Sox2 is a potential nuclear marker of cervical carcinoma." (PMID 24489842, 2014). "Also, expression of SOX2 was evaluated in normal and pathologic cervical tissues, and in cervical cancer tumorspheres and differentiated cells." (PMID 23782518, 2013). "Furthermore, DDR1 was transcriptionally regulated by SOX2 and might be a probable biomarker in cervical cancers." (PMID 39567474, 2024). "The stem cell signaling molecules (Notch related) were overexpressed in cervical cancer adherent cells as a result of 1 Gy C-ion, but there was no change in the expression level of these molecules along with other cancer stem cell markers (Nanog, SOX2 and OCT4A) in the spheroid populations." (PMID 34765546, 2021). "Therefore, the analysis of such possible interactions in cervical cancer cells could provide relevant information for understanding the mechanisms of transcriptional regulation of HPV by SOX2." (PMID 28678184, 2017). "Moreover, OCT-4 overexpression in the absence of SOX2 expression is strongly associated with poor prognosis in cervical cancer." (PMID 28212529, 2017). "Furthermore, cervical cancer with high SOX2 expression is more poorly differentiated, indicating that SOX2 might be a marker for undifferentiated cervical cancer." (PMID 27343550, 2017). "Sox2 could enhance the proliferation of cervical cancer cells by upregulating cyclin D1 expression." (PMID 26832364, 2016). "Moreover, in cervical cancer cells, Piwil2 overexpression also induced a significant upregulation of c-Myc, Nanog, Oct4, Sox2, and Klf4, increased the proportion of cells that were ALDH, MSCA-1, and ABCG2 positive and subsequently increased cisplatin resistance." (PMID 27602489, 2016). "Additionally, because more SiHa and C33A cells endogenously expressed Sox2 compared to HeLa and CaSki cells, the SiHa and C33A cell lines were chosen to evaluate whether endogenous Sox2-expressing cells are CSCs in cervical carcinomas." (PMID 24489842, 2014). "In the CaSki cervical cancer cell line, the expression of miR-122-5p is diminished, whereas UCA1 and SOX2 are significantly upregulated." (PMID 40710326, 2025). "Gremlin-1, a well-known antagonist of BMPs, promotes stemness by increasing the expression of OCT4, NANOG, and SOX2, as well as expanding the ALDH+ cell population in cervical cancer." (PMID 41373619, 2025). "In cervical cancer, inhibition of EGFR phosphorylation leads to downregulation of the stemness marker SOX2 and a reduction in the CSC population in CaSki and HeLa cell lines." (PMID 41373619, 2025). "In cervical cancer samples that we collected, the expression of DDR1 and SOX2 were increased, compared with paracancerous tissues." (PMID 39567474, 2024). "A PPIN of 90 genes identified FLT1, IGF2, IRS1, JUN, KDR, ZEB1, TIMP2 (downregulated), and EZH2, SOX2, and MYB (upregulated) in cervical cancer samples when compared with normal samples." (PMID 36879084, 2023). "In a review publication devoted to CSCs in cervical cancer, the following factors are included in the group of cancer stem cell markers: ABCG2, ALDH1, CD133, CD49f, OCT4, OPN, and SOX2." (PMID 34830452, 2021). "According to our previous studies, SOX2 and OCT4 play a crucial role in cervical cancer progression." (PMID 34489551, 2021).